CPEB2 (cytoplasmic polyadenylation element binding protein 2)
Diseases named in the same sentence as CPEB2 in open-access papers (continued):
Sharing a sentence is not in itself a finding about the gene and the disease.
tumor (16 papers, 2016 to 2025). "Functionally, CPEB2 exhibits tumor suppressor properties in HCC by inhibiting cell motility and colony formation in vitro and attenuating metastasis in vivo." (PMID 37514073, 2023). "To validate the role of p21 in CPEB2-mediated anti-tumor effect, we overexpressed p21 in CPEB2-knockdown cells." (PMID 38158431, 2023). "The identical CPEB2A of CPEB2 is a tumor suppressor and inhibits the translation of target mRNA, while the identical CPEB2 can competitively bind to the target RNA of CPEB2A, thus allowing subsequent translation." (PMID 36230487, 2022). "A tumor-suppressor role of CPEB2 was further suggested by its down-regulation by microRNA-885-5p, a mediator of EMT, tumorigenesis and metastasis in colorectal cancer." (PMID 31185986, 2019). "The role of CPEB2 in various tumor processes has been revealed." (PMID 37231521, 2023). "Importantly, studies had indicated that CPEB2 regulated the stability of many mRNAs, thereby affecting tumor progression." (PMID 37231521, 2023). "Previous study suggested that CPEB2 acted as tumor promotor in endometrial carcinoma, which overexpression could accelerate cell proliferation and inhibit apoptosis." (PMID 37231521, 2023). "Moreover, the results of xenograft tumor experiments showed that interference of CPEB2 also reduced the tumorigenesis of MM in vivo." (PMID 37231521, 2023). "Interestingly, mutating the CPEB2 m6A site increased BTB permeability and promoted Dox entry into tumor cells." (PMID 36064747, 2022). "Present study, utilizing in vitro and in vivo functional assays in CPEB2-depleted mammary epithelial cells as well as human breast-derived non-tumor and cancerous tissues, demonstrates that CPEB2, presumably the isoform A, plays a key role in suppressing tumorigenesis in mammary epithelial cells." (PMID 31185986, 2019). "CPEB2 protein was detected in reactive astrocytes, in normal brain tissue and in endothelial cells of tumors, indicating that stimulation of protein synthesis occurs in the direct proximity of blood vessels in newly formed tumor tissue." (PMID 27256982, 2016). "In the HCC tissues, our data demonstrated that CPEB2 was significantly downregulated, and its lack of expression was linked to poor clinical outcomes, including tumor recurrence and vascular invasion, which is consistent with the findings already reported in previous studies." (PMID 37514073, 2023). "Besides, CPEB2 silencing also reduced MM tumor growth by decreasing ARPC5 expression." (PMID 37231521, 2023). "We tested whether CPEB2 is a tumor suppressor in mammary epithelial cells." (PMID 31185986, 2019). "The methyl transferase METTL3 is up-regulated in brain tumors leading to the methylation of CPEB2 mRNA, which in turn stabilizes the splicing factor SRSF5 mRNA, leading to the incorporation of exon 7 in ETS-1 in models of the Blood–Tumor Barrier." (PMID 36064747, 2022). "The only COX-2 down-regulated gene targeted by both microRNAs was identified as Cytoplasmic Polyadenylation Element-Binding Protein 2 (CPEB2), the functions of which in tumor biology remain controversial." (PMID 31185986, 2019). "We showcase that miR-210-3p could regulate CPEB2 expression, and they were inversely correlated in HCC tumor tissues." (PMID 37514073, 2023). "While there was no scope for evaluating anti-angiogenic functions of CPEB2 in this study, the tumor suppressor properties of CPEB2 were ascribed to its splice variant CPEB2A." (PMID 33668160, 2021). "Predictions based on the LINC00899/PSMG3-AS1/PAXIP1-AS1- hsa-miR-210-3p-CPEB2 and SNHG16- hsa-miR-190b-BCL11A ceRNA regulation networks indicated that the two genes might act as tumor suppressor and oncogene, respectively." (PMID 33344235, 2020). "A negative connection between CPEB2 and miR-210-3p was found in the HCC tumor tissues." (PMID 37514073, 2023). "For CPEB2 and CPEB4 no methylation was detected in any of the investigated tumor specimens." (PMID 27256982, 2016).
cancer (5 papers, 2019 to 2023). A tumor composed of atypical neoplastic, often pleomorphic cells that invade other tissues. "CPEB2 (posterior probability = 0.89) is a regulator of translation, splice variants of which have been linked to cancer metastasis." (PMID 37745713, 2023). "The function of CPEB2 in cancer appears to be complex and paradoxical, depending on the expression of different CPEB2 isoforms." (PMID 38158431, 2023). "The CPEB2B splicing isoform with the inclusion of exon 4 into the mature CPEB2 mRNA was overexpressed in aggressive forms of human breast cancer and enhanced cancer metastasis was observed." (PMID 31737791, 2019). "The role of CPEB2 in cancer appear to be more complex and remains paradoxical." (PMID 38158431, 2023). "Up to published results, the selected genes were either playing a role in cancer development as Dmbt1, considered candidate tumor suppressor genes for several cancer types, or suppressors of mRNA translation and protecting from cancer development as Cpeb2." (PMID 30621213, 2019). "Two CPEB2 splicing isoforms with or without exon 4 was reported to mediate opposing effects on cancer-related phenotypes." (PMID 31737791, 2019). "Moreover, we found that CPEB2 inhibited EMT phenotypes in HCC, further supporting its role as a crucial factor in suppressing HCC metastasis, which has also been previously reported to promote differentiation and suppress EMT in a variety of cancer cells." (PMID 37514073, 2023).
CPEB2 also shares sentences with these, for which no sentence is quoted: astrocytoma (1 paper); Cognitive impairment (1); colon cancer (1); diabetes (1); multiple myeloma (1); nasopharynx cancer (1); oligodendroglioma (1); vitiligo (1).